FHL2 (four and a half LIM domains 2)
Diseases named in the same sentence as FHL2 in open-access papers (continued):
Sharing a sentence is not in itself a finding about the gene and the disease.
acute kidney injury (1 paper, 2024). Sudden and sustained deterioration of the kidney function characterized by decreased glomerular filtration rate, increased serum creatinine or oliguria. "Four-and-a-half LIM domains protein 2 (FHL2) is an adaptor protein that may interact with hypoxia inducible factor 1α (HIF-1α) or β-catenin, two pivotal protective signaling in acute kidney injury (AKI)." (PMID 38814462, 2024).
adenoma (1 paper, 2010). A neoplasm arising from the epithelium. "Moreover, the positive effects of FHL2 mutation on cell migration in ApcΔ14/+FHL2−/− mice correlate with the observation that FHL2 deficiency perturbs essentially adenoma initiation." (PMID 20442768, 2010). "Despite few adenomas developed at this stage, tumors occurred more frequently in ApcΔ14/+FHL2+/+ animals (73%, n = 11) than in ApcΔ14/+FHL2−/− littermates (40%, n = 10)." (PMID 20442768, 2010). "The mRNA levels of cyclin D1 and c-myc were indistinguishable in nontumor intestine between ApcΔ14/+FHL2+/+ and ApcΔ14/+FHL2−/− animals, and were strongly increased in adenomas from mice of both genotypes." (PMID 20442768, 2010). "Moreover, in keeping with the proliferative property of tumor cells, cyclin D1 was highly expressed in all adenomas, regardless of the FHL2 genotype." (PMID 20442768, 2010).
alcohol abusers (1 paper, 2021). "Since FHL2 is a locus where DNA methylation increases with age, this indicates slower aging in alcohol abusers." (PMID 34405265, 2021).
aplastic anemia (1 paper, 2021). Anemia resulting from bone marrow failure (aplastic or hypoplastic bone marrow). "Mutations in this gene were associated with multiple sclerosis, lymphoma, autoimmune lymphoproliferative syndrome (ALPS), aplastic anemia, and familial hemophagocytic lymphohistiocytosis type 2 (FHL2)." (PMID 34070492, 2021).
bone cancer (1 paper, 2013). A primary or metastatic malignant neoplasm affecting the bone or articular cartilage. "In this study, we determined the role of the multifunctional protein FHL2 in primary bone cancer growth and tumorigenesis in vitro and in vivo." (PMID 23383046, 2013). "However, the implication of FHL2 in primary bone cancer progression and tumorigenesis has not been investigated." (PMID 23383046, 2013).
bone tumor (1 paper, 2013). "In this study, we used a shRNA-based technique to study the contribution of FHL2 in primary bone tumor cell growth, invasion and migration, and we used xenograft experiments in mice to analyse the impact of FHL2 on tumorigenesis in vivo." (PMID 23383046, 2013). "Given the large impact of FHL2 silencing on K7M2 migration, we analyzed whether FHL2 silencing may also reduce bone tumor cell invasion." (PMID 23383046, 2013). "More importantly, FHL2 depletion greatly reduces tumor cell growth and metastasis, which raises the potential therapeutic interest of targeting FHL2 to efficiently impact primary bone tumors." (PMID 23383046, 2013). "We first investigated whether FHL2 expression is deregulated in bone tumor cells." (PMID 23383046, 2013).
cardiac ischemia (1 paper, 2017). "Recently, loss of FHL2 has been associated with an impaired inflammatory reaction after cardiac ischemia owing to a defect in immune cell migration." (PMID 28243234, 2017).
cervical squamous cell carcinoma (1 paper, 2025). A squamous cell carcinoma arising from the cervical epithelium. "For prognosis, high FHL2 expression was associated with poor OS in patients with THCA, cervical squamous cell carcinoma and endocervical adenocarcinoma (CESC), kidney renal clear cell carcinoma (KIRC), HNSC, LUAD, ovarian serous cystadenocarcinoma (OV), and LUSC." (PMID 40482916, 2025).
colon adenoma (1 paper, 2010). An adenoma that arises from the colon. "To assess the expression of FHL2 in human tumors, we analyzed five human colon adenomas with low-grade dysplasia, five human colon adenomas with high-grade dysplasia and five carcinomas by IHC for FHL2." (PMID 20442768, 2010).
colorectal tumors (1 paper, 2010). "In the study of human colorectal tumors, we found that FHL2 expression might be closely related to disease stages: the level of FHL2 in high-grade dysplasia is significantly elevated compared to normal tissues as well as low-grade dysplasia but clearly below that in carcinomas." (PMID 20442768, 2010).
dyslipidemia (1 paper, 2023). "In this study, we aimed to uncover the link between FHL2 genetic polymorphisms and dyslipidemia, as well as T2D, using the large multiethnic HELIUS cohort." (PMID 36901761, 2023). "In conclusion, our data indicate a link between FHL2 polymorphisms and dyslipidemia that is dependent on ethnic differences between individuals but does not occur through an effect on glucose metabolism." (PMID 36901761, 2023). "The association of human FHL2 with T2D and dyslipidemia in a multiethnic setting is unknown." (PMID 36901761, 2023). "Therefore, we used the large multiethnic Amsterdam-based Healthy Life in an Urban Setting (HELIUS) cohort to investigate FHL2 genetic loci and their potential role in T2D and dyslipidemia." (PMID 36901761, 2023). "The purpose of the current study was to determine whether FHL2 genetic loci are associated with the incidence of T2D and various aspects of lipid metabolism in a large multiethnic cohort (HELIUS cohort) and, thus, to further elucidate the role of FHL2 in human T2D and dyslipidemia." (PMID 36901761, 2023).
endometriosis (1 paper, 2025). The growth of functional endometrial tissue in anatomic sites outside the uterine body. "The results indicated that the C1 SFRP2+ Fibroblast and C3 RAMP1+ Fibroblast subpopulations predominantly originated from the Endometriosis tissue type, while the C0 FHL2+ Fibroblast and C2 CXCR4+ Fibroblast subpopulations were mostly derived from the Endometriomas tissue type." (PMID 41159025, 2025). "Regarding tissue type preference, the C0 FHL2+ Fibroblast and C2 CXCR4+ Fibroblast subpopulations were more common in Endometriomas, while the C3 RAMP1+ Fibroblast, C1 SFRP2+ Fibroblast, and C4 TFF3+ Fibroblast subpopulations were predominantly found in Endometriosis." (PMID 41159025, 2025).
epilepsy (1 paper, 2020). A brain disorder characterized by episodes of abnormally increased neuronal discharge resulting in transient episodes of sensory or motor neurological dysfunction, or psychic dysfunction. "Alternatively, the influence of FHL2 on dendritic modeling could be explained through interactions with the Wnt/β-catenin signaling pathway, which has been shown to refine dendrites in newborn DGCs and is also dysregulated in some forms of epilepsy." (PMID 32256309, 2020).
glomerular diseases (1 paper, 2019). "We also provide evidence that FHL2 levels are increased in subjects with different glomerular diseases other than hypertension, indicating that reduction of FHL2 may represent a novel therapeutic approach to kidney diseases." (PMID 31040292, 2019).
granulosa cell tumor (1 paper, 2023). A slow-growing, malignant tumor, characterize by the presence of granulosa-like cells and Call-Exner bodies, that is almost always found in the ovary. "We have shown that overexpression of FHL2 induces ovarian GC transformation and promotes granulosa cell tumor (GCT) progression." (PMID 37015904, 2023). "Our previous study also showed that FHL2 expression level was correlated with EGFR expression in the human granulosa cell tumor cell lines KGN and COV434." (PMID 37015904, 2023).
Griscelli syndrome type 2 (1 paper, 2018). Griscelli syndrome type 2 (GS2) is a rare, inherited condition that affects the skin, hair, and immune system. "In 13 out of the 24 (52%) a genetic diagnosis was achieved: PRF1 n = 4 (FHL2), STX11 n = 2 (FHL4), and STXBP2 n = 4 (FHL5), RAB27A n = 2 (Griscelli syndrome type 2), BIRC4 n = 1 (XIAP)." (PMID 30697212, 2018).
HCMV infection (1 paper, 2026). "Interestingly, during HCMV infection, HCMV replication-related protein UL84 was determined to interact with FHL2 to help the virus evade innate immune response and promote viral lytic origin (oriLyt) dependent DNA replication." (PMID 41587224, 2026).
hemophagocytic lymphohistiocytosis (1 paper, 2018). "This may indicate a major difference between murine FHL2 and FHL4, highlighting the pitfalls of extrapolating from one model of hemophagocytic lymphohistiocytosis to another." (PMID 30515155, 2018).
Hyperglycemia (1 paper, 2023). An increased concentration of glucose in the blood. "In doing so, we illustrate for the first time the association of several FHL2 polymorphisms with plasma lipid concentrations and hyperglycemia." (PMID 36901761, 2023).
Hypertension (1 paper, 2019). The presence of chronic increased pressure in the systemic arterial system. "To study the potential roles of the elevated FHL2 in hypertensive kidney disease, we used a continuous angiotensin II-induced hypertension model in FHL2 knockout mice and their wild-type littermates." (PMID 31040292, 2019). "Protein expression was examined by immuno-fluorescent staining, agree with transcriptional changes, FHL2 protein expression is also higher in hypertension samples." (PMID 31040292, 2019). "Since in vitro experiments suggest FHL2 facilitate FAK activity to turn-on Rac1 in hypertensive podocytopathy, we therefore isolated glomeruli from the four groups of mice to analyze Rac1 activity in vivo." (PMID 31040292, 2019). "Systemic FHL2 knockout mice are viable, maintaining normal kidney structure and function, but are protected from hypertension induced podocyte FP effacement and proteinuria." (PMID 31040292, 2019). "Although had similar severity of hypertension and hemodynamic changes, FHL2 knockout mice were protected from hypertension induced albuminuria." (PMID 31040292, 2019). "Normotensive FHL2 KO mice have unchanged baseline Rac1 activity, but the upregulation of GTP-Rac1 level was significantly suppressed in hypertension compared to their hypertensive WT littermates." (PMID 31040292, 2019). "Genetic deletion of the FHL2 did not alter normal renal structure or function but mitigated hypertension-induced podocyte foot process effacement and albuminuria." (PMID 31040292, 2019). "FHL2 deletion does not affect GFR in baseline or after hypertension." (PMID 31040292, 2019).
Immunodeficiency (1 paper, 2018). Failure of the immune system to protect the body adequately from infection, due to the absence or insufficiency of some component process or substance. "FHL2 is a fatal immunodeficiency condition, caused by PRF1 gene mutations exhibiting manifestations in immune cells that lead to systemic inflammation and multiorgan failure." (PMID 30021624, 2018).
Infertility (1 paper, 2025). "In our study, we sought to investigate the possible involvement of the ELOVL2, TRIM59, C1orf132, FHL2, and KLF14 genes in reproductive aging, infertility, and outcomes of ART." (PMID 40558830, 2025).
insulinoma (1 paper, 2022). "To unravel the underlying mechanism of improved GSIS by FHL2 deficiency, we initiated experiments in the insulinoma beta cell line MIN6." (PMID 35802167, 2022).
ischemia reperfusion injury (1 paper, 2024). Adverse functional, metabolic, or structural changes in ischemic tissues resulting from the restoration of blood flow to the tissue (reperfusion), including swelling; hemorrhage; necrosis; and damage from free radicals. "We found that FHL2 was induced in renal tubular cells in patients with acute tubular necrosis and mice model of ischemia-reperfusion injury (IRI)." (PMID 38814462, 2024).
liver dysfunction (1 paper, 2017). "FHL2 is clinically characterized by fever, edema, hepatosplenomegaly, and liver dysfunction." (PMID 28468610, 2017).
metastatic cancer (1 paper, 2015). A carcinoma which has spread from the original site of growth to another anatomic site. "To validate our findings in vivo, we detected FHL2 and KLF8 in serial sections of lymph node metastatic cancer tissues as exemplified in two patients." (PMID 26320172, 2015).
muscular dystrophy (1 paper, 2024). Muscular dystrophy (MD) refers to a group of more than 30 genetic diseases characterized by progressive weakness and degeneration of the skeletal muscles that control movement. "This shows that Fhl2 is more widespread in several different cytoskeletal gene mutations and models for muscular dystrophy." (PMID 38431640, 2024). "We therefore propose that Fhl2 based therapy has the potential to be utilized to alleviate muscular dystrophy in body musculature." (PMID 38431640, 2024). "This notion is strengthened by the fact that we found Fhl2 to be more abundant in a number of muscular dystrophy models, suggesting it is part of a general mechanism of defense in the EOMs." (PMID 38431640, 2024). "Our study shows Fhl2 upregulation in EOMs of several disease models, suggesting that Fhl2 is a strong candidate for the development of future therapeutic strategies for a common management of muscular dystrophies." (PMID 38431640, 2024). "Next, we asked whether an increase in Fhl2 positive myofibers of EOMs could be found across muscular dystrophies and therefore immunolabeled plecb−/− (plectin) and obscnb−/− (obscurin) mutant zebrafish EOMs, both resulting in muscular dystrophy when mutated in other models." (PMID 38431640, 2024). "In summary, Fhl2 is present in EOMs across different muscular dystrophies and species and is increased with the progression of the disease in the EOMs of desma-/-;desmb-/- mutant zebrafish." (PMID 38431640, 2024). "Therefore, Fhl2 is a protective agent and a candidate target gene for therapy of muscular dystrophies." (PMID 38431640, 2024). "Since fhl2b was the only Fhl2 paralog differentially expressed in our transcriptomic data of EOMs lacking desmin, we chose to investigate whether fhl2b also could protect muscles other than EOMs in muscular dystrophy." (PMID 38431640, 2024).
Neonatal sepsis (1 paper, 2025). Systemic inflammatory response to infection in newborn babies. "These include a fatal neonatal FHL2 with compound PRF1 variants and absent perforin expression, and an early-infant FHL2 that presented as late-onset neonatal sepsis before genetic confirmation." (PMID 41477640, 2025).
oral squamous cell carcinoma (1 paper, 2021). "Among the target genes, Fhl2 was reported to contribute to tongue squamous cell carcinoma and other cancers; Mapk6 is a Ser/Thr protein kinase and is related with oral squamous cell carcinoma and other cancers." (PMID 34409068, 2021).
ovarian tumors (1 paper, 2016). "By manipulating FHL2 expression in KGN cells and COV434 cell, our data indicate that FHL2 acts as a GCT tumor cell growth-promoting factor, implying that FHL2 may function as an oncogenic protein in ovarian tumors." (PMID 27415427, 2016). "The mechanism by which FHL2 regulates the ovarian tumor cell growth is also unclear." (PMID 27415427, 2016). "In the present study, we indicated that FHL2 is a key regulator of AKT1 gene expression, at least in the ovarian tumor cell lines." (PMID 27415427, 2016).
polycystic ovary syndrome (1 paper, 2023). A disorder that manifests as multiple cysts on the ovaries. "It is worthy to notice that FHL2 was upregulated in human GCs or ovarian tissues of polycystic ovary syndrome (PCOS) patients." (PMID 37015904, 2023).
polyp (1 paper, 2010). A usually exophytic mass attached to the underlying tissue by a broad base or a thin stalk. "Precisely, while the polyp number in ApcΔ14/+FHL2+/+ could reach more than 40, the great majority of ApcΔ14/+FHL2−/− mice developed less than 9 tumors and none of the animals had more than 19 polyps." (PMID 20442768, 2010).
Sepsis (1 paper, 2025). Sepsis is defined as life-threatening organ dysfunction caused by a dysregulated host response to infection. "We report a fulminant neonatal FHL2 case associated with biallelic PRF1 variants that initially mimicked sepsis." (PMID 41477640, 2025). "Truncating PRF1 alleles are loss-of-function and align with neonatal-/early-infant-onset FHL2; notably, c.65delC has been reported among recurrent alleles in Chinese cohorts, and neonatal, sepsis-like courses have been described in FHL2." (PMID 41477640, 2025).
Streptococcus pneumoniae Infection (1 paper, 2017). "It is of note that we did not observe any NK cell proliferation nor apoptosis during the early course of pneumococcal infection in WT mice as well as in FHL2−/− mice (data not shown)." (PMID 28243234, 2017).
tendinopathy (1 paper, 2025). "This study revealed that low FHL2 expression-induced upregulation of YAP1/sFRP2 may be a critical mechanism underlying vascular remodeling in tendinopathy." (PMID 41258071, 2025). "This study employed exercise-induced (treadmill) and trauma-induced rat tendinopathy models to investigate the FHL2/YAP1/sFRP2 axis in the context of angiogenesis." (PMID 41258071, 2025). "Our findings demonstrated that FHL2 supplementation after tendon injury can noticeably decrease YAP1/sFRP2 expression, inhibit vascular remodeling associated with tendinopathy and restore tissue structure despite some differences from normal tendon tissue." (PMID 41258071, 2025). "This study reveals that FHL2/YAP1/sFRP2-mediated vascular remodeling drives tendinopathy progression." (PMID 41258071, 2025). "In conclusion, this study systematically explored the progression of tendinopathy and its pathological relationship with vascular instability, highlighting the critical role of vascular remodeling via the FHL2/YAP1/sFRP2 signaling axis." (PMID 41258071, 2025). "By contrast, downregulation of FHL2 expression and upregulation of YAP1/sFRP2 expression are strongly and positively correlated with the temporal pathological remodeling and angiogenesis associated with tendinopathy." (PMID 41258071, 2025). "Therefore, the reduced vessel abundance and complexity observed here probably reflect the unique role of FHL2 within the specific inflammatory microenvironment of tendinopathy." (PMID 41258071, 2025). "Finally, adenoassociated virus (AAV) vectors were employed to explore the feasibility of FHL2 gene therapy for reversing vascular remodeling in tendinopathy." (PMID 41258071, 2025). "Thus, in tendinopathy, FHL2 overexpression may primarily suppress inflammatory angiogenesis via its anti-inflammatory effects, thereby improving perfusion and promoting repair, potentially mediated by the YAP1/sFRP2 axis." (PMID 41258071, 2025).
Venous thrombosis (1 paper, 2021). Formation of a blood clot (thrombus) inside a vein, causing the obstruction of blood flow. "Furthermore, FHL2 SNP rs4851770 was shown to associate with the risk of developing venous thrombosis in humans." (PMID 34685595, 2021).
vitiligo (1 paper, 2022). Generalized well circumscribed patches of leukoderma that are generally distributed over symmetric body locations and is due to autoimmune destruction of melanocytes. "To further determine the in situ distributions of sPmel17, FHL2, and E-cadherin, we examined the expression profiles of those proteins in the skin from healthy subjects and from depigmented or repigmented vitiligo using immunofluorescence and immunohistochemical staining." (PMID 35186181, 2022). "The results showed that immunoreactivities with anti-sPmel17 and anti-FHL2 antibodies almost completely disappeared in the vitiliginous lesions; however, the restoration of immunostaining using those same antibodies was found in the repigmented skins from the same vitiligo patients." (PMID 35186181, 2022). "To this end, we used immunofluorescence and immunohistochemistry to examine the expression profiles of FHL2 and sPmel17 in UVB-treated tail skin of Dct-LacZ transgenic mice and the repigmented lesional skins from vitiligo patients who underwent UVB therapy." (PMID 35186181, 2022). "Furthermore, skin biopsy specimens were taken at the site of vitiliginous lesions and repigmented skin from 7 vitiligo patients with UVB-induced repigmentation and the expression profiles of sPmel17 and FHL2 were detected in those specimens using immunohistochemical staining." (PMID 35186181, 2022).